ENSG00000228165 (miR-101-precursor-9 micro RNA)
Gene: Long non-coding RNA gene on chromosome 9 (4,850,299 to 4,850,373, reverse strand). Ensembl gene ENSG00000228165.
Gene Ontology:
Biological process: miRNA-mediated post-transcriptional gene silencing
Cellular component: RISC complex